ANKRD31 (ankyrin repeat domain 31)
Description:
Required for DNA double-strand breaks (DSBs) formation during meiotic recombination. Regulates the spatial and temporal patterns of pre-DSB recombinosome assembly and recombination activity by acting as a scaffold that anchors REC114 and other factors to specific genomic locations, thereby regulating DSB formation. Plays a key role in recombination in the pseudoautosomal regions of sex chromosomes.
Synonyms: FLJ40191
Tractability: No criterion of Open Targets' tractability assessment is met for any kind of drug.
Gene: Protein-coding gene on chromosome 5 (75,068,275 to 75,236,911, reverse strand). Ensembl gene ENSG00000145700.
Subcellular location: Nucleus; Chromosome
Subcellular location (Human Protein Atlas): Centrosome; Nucleoplasm; Nucleoli; Vesicles
Gene Ontology:
Biological process: homologous chromosome pairing at meiosis; meiotic DNA double-strand break formation involved in reciprocal meiotic recombination; positive regulation of meiotic DNA double-strand break formation
Cellular component: chromatin; chromosome; nucleus
Genetic constraint (gnomAD): Loss-of-function variants: 101 observed, 141.2 expected, observed/expected ratio (o/e) 0.72, 90% interval 0.61 to 0.84. The upper end of that interval is the gene's LOEUF score, 0.84, which puts it in group 3 of 6, group 1 being the genes least tolerant of losing a copy. Missense variants: 1,763 observed, 1,974.3 expected, observed/expected ratio (o/e) 0.89, 90% interval 0.86 to 0.93. Synonymous variants: 607 observed, 691.25 expected, observed/expected ratio (o/e) 0.88, 90% interval 0.82 to 0.94.
Homologues: Orthologues: chimpanzee ANKRD31 (99% identical), macaque ANKRD31 (89% identical), dog ANKRD31 (68% identical), pig ANKRD31 (67% identical), guinea pig ANKRD31 (56% identical), mouse Ankrd31 (52% identical), rat Ankrd31 (38% identical), tropical clawed frog ankrd31 (16% identical), Drosophila melanogaster pain (9% identical). Paralogues in human: ANKRD36C (8% identical), ANKRD36 (8% identical), ANKRD36B (8% identical).
Diseases named in the same sentence as ANKRD31 in open-access papers:
ANKRD31 is named in the same sentence as 4 diseases in open-access papers, as found by Europe PMC text mining. Sharing a sentence is not in itself a finding about the gene and the disease. The quoted sentences say what the papers report.
Infertility (3 papers, 2022 to 2023). "However, a specific gene of this family seems to be involved in reproduction as Ankrd31−/− mice are infertile possibly due to deregulation of the blood-epididymal barrier." (PMID 36140773, 2022).
Premature ovarian insufficiency (3 papers, 2021 to 2023). Amenorrhea due to loss of ovarian function before the age of 40. "In clinical studies, two heterozygous variants (p.Gln 329* and c.1565–2A>G (splice donor before exon 11)) in ANKRD31 were found in patients with premature ovarian insufficiency (POI)." (PMID 37162821, 2023).
teratozoospermia (1 paper, 2021). "Ankrd31–/– mice were infertile and exhibited oligo-astheno-teratozoospermia (a low number of immotile SPZ with abnormal morphological features)." (PMID 34820371, 2021).
ANKRD31 also shares sentences with these, for which no sentence is quoted: asthenozoospermia (1 paper).